TRIM59 (tripartite motif containing 59)
Description:
E3 ubiquitin ligase involved in different processes such as development and immune response. Serves as a negative regulator for innate immune signaling pathways by suppressing RLR-induced activation of IRF3/7 and NF-kappa-B via interaction with adapter ECSIT. Regulates autophagy through modulating both the transcription and the ubiquitination of BECN1. On the one hand, regulates the transcription of BECN1 through negatively modulating the NF-kappa-B pathway. On the other hand, regulates TRAF6-mediated 'Lys-63'-linked ubiquitination of BECN1, thus affecting the formation of the BECN1-PIK3C3 complex. In addition, mediates 'Lys-48'-linked ubiquitination of TRAF6 and thereby promotes TRAF6 proteasomal degradation. Also acts as a critical regulator for early embryo development from blastocyst stage to gastrula through modulating F-actin assembly and WASH1 'Lys-63'-linked ubiquitination (By similarity).
Synonyms: RNF104; TRIM57; TSBF1; Mrf1; IFT80L
Tractability: Antibody: UniProt predicts a signal peptide or a membrane-spanning region. PROTAC: ubiquitination databases record sites on it.
Target class: Enzyme; Transferase
Gene: Protein-coding gene on chromosome 3 (160,432,445 to 160,485,773, reverse strand). Ensembl gene ENSG00000213186.
Subcellular location: Endoplasmic reticulum membrane
Gene Ontology:
Molecular function: protein binding; ubiquitin protein ligase activity; zinc ion binding
Biological process: negative regulation of canonical NF-kappaB signal transduction; innate immune response; antiviral innate immune response; host-mediated suppression of symbiont invasion; protein ubiquitination
Cellular component: endoplasmic reticulum membrane; endoplasmic reticulum; intraciliary transport particle B
Genetic constraint (gnomAD): Loss-of-function variants: 15 observed, 34.21 expected, observed/expected ratio (o/e) 0.44, 90% interval 0.29 to 0.68. The upper end of that interval is the gene's LOEUF score, 0.68, which puts it in group 2 of 6, group 1 being the genes least tolerant of losing a copy. Missense variants: 471 observed, 484.9 expected, observed/expected ratio (o/e) 0.97, 90% interval 0.9 to 1.05. Synonymous variants: 163 observed, 162.32 expected, observed/expected ratio (o/e) 1, 90% interval 0.88 to 1.14.
Homologues: Orthologues: macaque TRIM59 (95% identical), dog TRIM59 (89% identical), pig TRIM59 (87% identical), rabbit TRIM59 (84% identical), rat Trim59 (84% identical), mouse Trim59 (83% identical), guinea pig TRIM59 (76% identical), Drosophila melanogaster Oseg5 (11% identical), Caenorhabditis elegans che-2 (7% identical). Paralogues in human: IFT80 (13% identical).
Diseases named in the same sentence as TRIM59 in open-access papers:
TRIM59 is named in the same sentence as 63 diseases in open-access papers, as found by Europe PMC text mining. Sharing a sentence is not in itself a finding about the gene and the disease. The quoted sentences say what the papers report.
lung carcinoma (27 papers, 2017 to 2025). "Thus, we conclude that lung cancer cells secrete exosomal TRIM59 that directly targets ABHD5, leading to ABHD5 deficiency in TAMs." (PMID 32867817, 2020). "TRIM59 promotes lung cancer progression by regulating autophagy or the NLRP3 inflammasome signalling pathway." (PMID 38291200, 2024). "A previous study revealed that TRIM59 is highly expressed and contributes to gefitinib resistance in lung cancer." (PMID 39725730, 2024). "Another study revealed that TRIM59 is highly expressed in lung cancer and contributes to gefitinib resistance in EGFR mutant (Mut) lung adenocarcinomas." (PMID 39725730, 2024). "TRIM59 has a high expression level in a variety of lung cancer cell lines, while knockdown of which can affect the expression of cyclins (including CDC25C and CDK1), thereby enhancing the proliferative and migratory abilities of lung cancer cells." (PMID 35912155, 2022). "The correlation between the expression level of TRIM59 in lung cancer and the abundance of immune cell invasion was analyzed by TIMER database." (PMID 34397900, 2021). "In this study, the application of meta-analysis and bioinformatics analysis will provide evidence support for the study on the prognosis and mechanism of TRIM59 in lung cancer." (PMID 34397900, 2021). "In this study, the role of TRIM59 in the prognosis of lung cancer patients was analyzed through meta-analysis and bioinformatics." (PMID 34397900, 2021). "In recent years, related studies have revealed that tripartite motif-containing 59 (TRIM59) is related to the prognosis of lung cancer." (PMID 34397900, 2021). "The mRNA expression level of TRIM59 in lung cancer was analyzed using Oncomine and Gene Expression Profiling Interactive Analysis (GEPIA) database." (PMID 34397900, 2021). "Taken together, these results clearly demonstrated that TRIM59 is expressed in lung cancer cells-derived exosomes, and can be transferred to macrophages through the exosomes." (PMID 32867817, 2020). "For example, the expression of TRIM59 in the lung carcinoma cell line H1299 inhibits autophagy by negatively regulating the expression of Becn1 mRNA, an effect that was connected to TRIM59's observed inhibitory action on NF-κB activation." (PMID 32226386, 2020). "We demonstrated that tripartite motif-containing 59 (TRIM59) was expressed in lung cancer cells-derived exosomes, and can be transferred to macrophages through the exosomes." (PMID 32867817, 2020). "Our previous study has demonstrated that TRIM59 upregulated in lung cancer, is required for cancer cells survival and metastasis." (PMID 32867817, 2020). "First, it was observed that TRIM59 can be delivered into the macrophages by exosomes derived from lung cancer cells." (PMID 32867817, 2020). "We previously found that TRIM59 is closely correlated with oncogenesis and metastasis of lung cancers." (PMID 32867817, 2020). "We found that TRIM59 was detected in the exosomes of lung cancer cells, whereas the levels of TRIM59 in both lung cancer cells and exosomes were strongly decreased by transfection of shTRIM59." (PMID 32867817, 2020). "Collectively, these data provide evidence that TRIM59 is involved in lung carcinoma growth and progression possibly through the induction of CDK6 expression and EMT process by activation of ERK pathway." (PMID 30515965, 2019). "TRIM59 is critical for tumor growth in human prostate cancer, lung cancer, osteosarcoma, and cervical cancer." (PMID 31488827, 2019). "Using bioinformatics analysis and immunohistochemical of lung carcinoma tissues, we show that TRIM59 as a critical oncoprotein relating to LC proliferation and metastasis." (PMID 30515965, 2019). "SiRNA-induced knockdown of TRIM59 significantly inhibited the proliferation and migration of lung cancer cells by increasing the expression of a number of cell cycle proteins including CDC25C and CDK136." (PMID 28211536, 2017).
lung carcinoma (continued). "Therefore, this study evaluated the relationship between TRIM59 and the prognosis of lung cancer by carrying out meta-analysis." (PMID 34397900, 2021). "Therefore, in this study, bioinformatics analysis and meta-analysis were used to explore the expression and potential function of TRIM59 in lung cancer, so as to provide reference for relevant basic experiments and clinical translational studies." (PMID 34397900, 2021). "In addition, we explored the mechanism and related pathways of TRIM59 in lung cancer through bioinformatics analysis." (PMID 34397900, 2021). "Activated macrophages by TRIM59 promote lung cancer progression in vitro and in vivo." (PMID 32867817, 2020). "To elucidate whether TRIM59 was expressed in exosomes derived from lung cancer cells (H1299 and A549), we detected the expression of TRIM59 in the exosomes derived from A549 and H1299 cell lines, in which TRIM59 expression levels significantly elevated." (PMID 32867817, 2020). "Interestingly, in this study, we demonstrated that macrophages were educated by TRIM59 promote lung cancer cells progression." (PMID 32867817, 2020). "Moreover, TRIM59 is involved in lung carcinoma growth and invasion through the induction of CDK6 expression and EMT progression by activation of the ERK pathway." (PMID 30515965, 2019). "In summary, our data identify TRIM59 as a key promoter of tumour progression, which uncovers that TRIM59 may become a prognostic marker and therapeutic target for lung carcinoma." (PMID 30515965, 2019). "TRIM59 has also been reported to be involved in certain types of human cancer, The expression level of TRIM59 has been shown to be upregulated in many cancers including lung cancer, gastric cancer, breast cancer, hepatocellular carcinoma, colorectal cancer, and others." (PMID 31770215, 2019). "Among all the TRIM genes, TRIM59 was found to be the only member displaying marked up-regulation across all the 12 cancer types, a discovery that concurs with the recent findings that TRIM59 promotes the progression of prostate cancer, lung cancer, and gastric cancer." (PMID 30408026, 2018). "However, the expression of TRIM59 and its function in lung cancer are still poorly understood." (PMID 34397900, 2021). "Tripartite motif-containing 59 (TRIM59) is expressed in lung cancer cell-derived exosomes and could be transferred to macrophages via exosomes, leading to macrophage activation, which in turn promotes lung cancer progression." (PMID 34281588, 2021). "To mimic the up-regulation of TRIM59 expression in TAMs and investigate its role in LC cells growth and metastasis in vivo, we utilized a CD11b promoter-driven macrophages-specific TRIM59 transgenic (TgTRIM59) mouse model, in which the lewis lung carcinoma (LLC) cells were inoculated subcutaneously." (PMID 32867817, 2020). "Thus, we detected whether TRIM59 could be transferred from lung cancer cells to macrophages via exosomes." (PMID 32867817, 2020). "(2020) showed that lung cancer cells release exosomes containing TRIM59, an E3 ligase, which are transferred to macrophages, leading to NLRP3 inflammasome activation and promoting lung cancer progression." (PMID 40692785, 2025). "A recent study demonstrated that tumor-derived exosomal TRIM59 activates NLRP3 inflammasomes in macrophages and promotes their pro-tumor M2 polarization, thereby promoting lung cancer progression." (PMID 39494337, 2024). "Tumor-derived exosomal TRIM59 induces the tumor-promoting function of macrophages to activate the NLRP3 inflammasome signaling pathway, thereby promoting lung cancer progression." (PMID 36118863, 2022). "We also combined GEO datasets and performed a meta-analysis to reveal that high expression of TRIM59 showed significant (p<0.05) poor prognosis in KIRP, LGG, LUAD, lung cancer and showed better prognosis in CESC and SKCM." (PMID 34534244, 2021).
lung carcinoma (continued). "The six articles included in this study indicated that TRIM59 was related to TNM (Tumor Node Metastasis) in hepatocellular carcinoma, lung cancer, colorectal cancer, and breast cancer." (PMID 31770215, 2019). "In cancer, tumor‐derived exosomal TRIM59 could convert macrophages to a pro‐tumor phenotype via regulating ABHD5 proteasomal degradation, and led to NLRP3 inflammasome activation to promote lung cancer progression." (PMID 40135589, 2025). "Tumor-derived exosomal TRIM59 reprograms macrophages toward a tumor-promoting phenotype by inducing the proteasomal degradation of ABHD5, thereby activating the NLRP3 and enhancing lung cancer progression through increased IL-1β secretion." (PMID 40443670, 2025). "Liang and their colleagues found that cancer-derived exosomal TRIM59 could physically bind with ABHD5, further regulating macrophage and lung cancer progression." (PMID 36591493, 2022). "Exosomes derived from lung cancer cells secrete TRIM59 and transform macrophages into tumor-promoting macrophages by regulating ABHD5 proteasome degradation, which activates the NLRP3 inflammasome signaling pathway and promotes the progression of lung cancer by secreting IL-1." (PMID 34511114, 2021). "TRIM59 directly induces the ubiquitination of ABHD5, leading to its proteasome-dependent degradation, activating the NLRP3 inflammasome signaling pathway, and promoting the secretion of IL-1β by macrophages; As the final result, exosomal TRIM59 facilitates lung cancer growth and metastasis." (PMID 35047512, 2021). "In sum, our results showed that, tumor-derived exosomal TRIM59 converts macrophages to tumor-promoting functions of macrophages via regulating ABHD5 proteasomal degradation, to activate NLRP3 inflammasome signaling pathway to promote lung cancer progression by IL-1β secretion." (PMID 32867817, 2020). "Collectively, these data indicate that tumor-derived exosomal TRIM59 converts macrophages to tumor-promoting functions of macrophages via regulating ABHD5 proteasomal degradation, to activate NLRP3 inflammasome signaling pathway to promote lung cancer progression by IL-1β secretion." (PMID 32867817, 2020).
breast cancer (17 papers, 2018 to 2026). A primary or metastatic malignant neoplasm involving the breast. "Most clinically relevant, elevated TRIM59 expression was significantly associated with shortened breast cancer patient survival (P = 0.0244)." (PMID 30408026, 2018). "In summary, our study has unveiled TRIM59 as an essential tumor-promoting factor that facilitates breast cancer growth and metastasis through modulating PDCD10-associated signaling pathways, as well as other oncogenic pathways." (PMID 30408026, 2018). "In this study, we identified TRIM59 as a cancer-associated E3 Ub ligase, the expression of which was strongly associated with poor clinical outcomes in breast cancer patients." (PMID 30408026, 2018). "In addition, TRIM59 as an essential tumor-promoting factor that facilitates breast cancer growth and metastasis through modulating PDCD10-associated signaling pathways." (PMID 32867817, 2020). "In the xenograft models, overexpression of TRIM59 in MCF7 or MDA-MB-231 cells promoted pulmonary metastasis of breast cancer cells, whereas TRIM59 deficiency suppressed cancer cell metastasis, as reflected by cytokeratin 8 (CK8) staining of metastasized cancer cells in the lung." (PMID 30408026, 2018). "Suppression of TRIM59, a highly expressed E3 ligase in breast cancer with metastasis, inhibits metastasis by inducing RNFT1-induced K63 ubiquitination of PDCD10." (PMID 36202787, 2022). "TRIM59 (Tripartite motif protein 59) is another molecule investigated in one of the reviewed articles and overexpressed in breast cancer cells." (PMID 33498521, 2021). "A recent study reported that depletion of TRIM59 suppresses breast cancer metastasis by promoting RNFT1-induced K63 poly ubiquitination and SQSTM1-directed autophagic degradation of PDCD10." (PMID 31600735, 2019). "Bioinformatic analysis and experiments on clinical samples and mouse models of breast cancer unveil a new signaling protein degradation pathway involving TRIM59 and PDCD10 that modulates breast cancer cell growth, survival, and metastasis." (PMID 30408026, 2018). "Our findings establish that TRIM59 promotes the proliferation, migration, and invasion of breast cancer cells." (PMID 30408026, 2018). "Loss of TRIM59 or PDCD10 suppresses tumor growth both in vitro and in vivo, and the amount of both proteins inversely correlates with survival of breast cancer patients." (PMID 30408026, 2018). "Upon TRIM59 depletion or overexpression, we noticed prominent morphological changes in breast cancer cells." (PMID 30408026, 2018). "Collectively, results from our in vivo studies further reinforced the conclusion that TRIM59 plays a pro-oncogenic role in breast cancer by promoting tumor cell growth and migration." (PMID 30408026, 2018). "In parallel, we assessed the expression of TRIM59 mRNA in human and mouse tissues, as well as in a panel of human breast cancer cell lines, by using the mammary epithelial cell line MCF10A as a nonmalignant control." (PMID 30408026, 2018). "To further verify the protein levels of TRIM59 in breast cancer patients, we performed immunohistochemistry (IHC) staining for TRIM59 on primary human breast tumors obtained from a large cohort of breast cancer patients." (PMID 30408026, 2018). "We further detected expression of TRIM59 in breast cancer cell lines, with the highest expression in cell lines such as MCF7 but relatively low expression in cell lines such as MDA-MB-231." (PMID 30408026, 2018). "Collectively, these findings suggest that TRIM59 promotes breast cancer growth and migration/invasion through PDCD10-induced suppression of ROCK signaling and subsequent MAT." (PMID 30408026, 2018). "We found a significantly higher expression of TRIM59 in metastatic breast cancer at both mRNA and protein levels." (PMID 30408026, 2018).